ZIC2 (Zic family zinc finger 2)
Diseases named in the same sentence as ZIC2 in open-access papers (continued):
Sharing a sentence is not in itself a finding about the gene and the disease.
small cell lung carcinoma (4 papers, 2009 to 2023). Small cell lung cancer (SCLC) is a highly aggressive malignant neoplasm, accounting for 10-15% of lung cancer cases, characterized byrapid growth, and early metastasis. "The presence of SOX Group B and/or ZIC2 AAs are frequently observed in small cell lung carcinoma (SCLC), and were also reported to be indicators of a better prognosis." (PMID 20854674, 2010). "A study into antibodies against ZIC2 in small lung cell carcinoma showed that the concentration of antibodies is a good indicator of prognosis." (PMID 19208118, 2009). "Autoantibodies in small lung cell carcinoma patients show cross-reactivity among ZIC1, ZIC2, and ZIC4 proteins, suggesting that immunoreactivities of the autoantibodies are directed primarily against the conserved zinc finger domains of ZIC." (PMID 20199689, 2010).
spina bifida (4 papers, 2007 to 2023). A congenital neural tube defect in which vertebrae are not fully formed. "In order to further unravel the molecular pathogenesis of spina bifida in the ZicKu model, it will be important to determine the pathways that link function of Zic2 with regulation of the critical BMP and RhoA signalling pathways that we have identified." (PMID 36916392, 2023). "Although only small numbers of embryos were obtained with the less frequent Zic2/Shh genotypes, the data are consistent with a lack of spina bifida rescue by Shh loss of function." (PMID 36916392, 2023). "Lack of Zic2 causes a delay in neurulation, spina bifida, and at a lower rate, exencephaly." (PMID 17996054, 2007). "Hence, mouse embryos lacking Zic2 function specifically fail in DLHP development, and this seems to be a likely cause of spinal closure arrest and origin of spina bifida in these embryos." (PMID 36916392, 2023). "Zic2/Zic3 double mutants exhibit craniorachischisis though this may be a result of exencephaly and severe spina bifida, rather than a failure of closure 1; genetic interaction between Zic mutants and the PCP pathway has not been assessed." (PMID 20704721, 2010).
acute myeloid leukemia (3 papers, 2021 to 2024). Acute myeloid leukemia (AML) is a group of neoplasms arising from precursor cells committed to the myeloid cell-line differentiation. "We select six representative genes from CancerMine, which include three most frequently reported genes in the context of acute myeloid leukemia (AML), KMT2A, FLT3, and MLLT3, as well as three genes that are least reported in this specific cancer, namely ZFP36L2, ZIC2, and ZNF582." (PMID 38431735, 2024).
epithelial ovarian tumor (3 papers, 2019 to 2023). "ZIC2 is an oncogenic with overexpression correlated with progression of epithelial ovarian tumors." (PMID 35565241, 2022).
lung carcinoma (3 papers, 2021 to 2022). "Evidence has demonstrated that homeobox (HOX) A1 (HOXA1) and HOXA11 play oncogenic roles in lung cancer, and they are the putative target genes of miR-181c-3p, as same as ZIC2, as analyzed by the bioinformatics analysis using the starBase database." (PMID 34232917, 2021). "Notably, ZIC2, which represses primary neurogenesis and modulates primary neurogenesis apoptosis in the neural plate, is typically overexpressed in Alzheimer's disease and lung cancer." (PMID 36518809, 2022).
meningioma (3 papers, 2010 to 2023). A generally slow growing tumor attached to the dura mater. "This is consistent with our observation that ZIC1, ZIC2 and ZIC5 mRNA levels are higher in meningiomas than in normal brain tissues." (PMID 20199689, 2010). "ZIC1, ZIC2, and ZIC5 are novel molecular markers for meningiomas whereas ZIC4 expression is highly selective for medulloblastomas." (PMID 20199689, 2010). "We examined the mRNA and protein expression of human ZIC1, ZIC2, ZIC3, ZIC4 and ZIC5 genes in meningiomas in comparison to other brain tumors, using RT-PCR, analysis of published microarray data, and immunostaining." (PMID 20199689, 2010). "RT-PCR analysis revealed that ZIC4 expression is highly enhanced in medulloblastoma, in a sharp contrast to the expression levels in whole brain, while ZIC1, ZIC2 and ZIC5 are expressed both in the meningioma and medulloblastoma." (PMID 20199689, 2010). "Our results indicate that the expression of ZIC1, ZIC2 and ZIC5 is a conserved feature of meningioma." (PMID 20199689, 2010). "ZIC1, ZIC2 and ZIC5 transcript levels in meningiomas were higher than those in whole brain or normal dura mater, whereas all five ZIC genes were abundantly expressed in medulloblastomas." (PMID 20199689, 2010). "The transcriptional levels of ZIC1, ZIC2, and ZIC5 in meningiomas were found to be significantly higher than those in normal dura mater and could serve as new molecular markers for meningiomas." (PMID 37479694, 2023). "The mRNA levels of ZIC1, ZIC2 and ZIC5 were higher in meningioma than in dura mater." (PMID 20199689, 2010).
renal cell carcinoma (3 papers, 2023). "Firstly, we detected the expression level of ZIC2 in different kinds of renal cell carcinoma cell lines." (PMID 37496990, 2023). "Zic2 was required for RUNX2′s high expression in renal cell carcinoma." (PMID 37108164, 2023). "Relatively high RUNX2 levels were detected by IHC staining in tissues of renal cell carcinoma compared with nontumor tissue, whose regulatory mechanism required Zic family member 2 (Zic2) in 786-O and ACHN cells." (PMID 37108164, 2023).
brain malformation (2 papers, 2020 to 2025).
breast tumor (2 papers, 2023 to 2025). "Further research should focus on ZIC2’s specific interactions with lymphatic endothelial cells within the breast tumor microenvironment." (PMID 40895068, 2025). "In the SQ breast tumors, we observed significantly upregulated mRNA levels of the Oct3/4 regulatory network, including ONSS, and several other PTFs, including Nanog, Sall4, Sox2, Sox4, FoxA2, Gata6, Zic2 and HoxB7, as well as Oct3/4 isoform B, polycomb suppressors Bmi1, EzH2, Amigo and Dkk1." (PMID 37298091, 2023).
gastric cancer (2 papers, 2021 to 2025). A primary or metastatic malignant neoplasm involving the stomach. "For example, ZIC2 showed increased expression and was associated with tumorigenesis and poor outcome in a wide range of cancer types like meningiomas, pancreatic cancer, nasopharyngeal carcinoma, non-small cell lung cancer, neuroblastoma, and gastric cancer." (PMID 40952541, 2025). "We also determined that ZIC2 was highly expressed in breast, cervical, colorectal, and gastric cancers, using the Oncomine database." (PMID 33439969, 2021). "In gastric cancer, ZIC2 could enhance Wnt signaling by increasing the expression of β-catenin, c-Myc, and MMP-7, while repressing Axin expression." (PMID 40952541, 2025).
glioma (2 papers, 2021 to 2024). A benign or malignant brain and spinal cord tumor that arises from glial cells (astrocytes, oligodendrocytes, ependymal cells). "The neural development-associated TFs, ZIC1, ZIC2, and ZIC3, were specifically expressed in glioma." (PMID 39345334, 2024). "The expression of ZIC2 between glioma tissues and corresponding normal samples had no obvious difference." (PMID 34475426, 2021).
leukemia (2 papers, 2020 to 2021). A malignant (clonal) hematologic disorder, involving hematopoietic stem cells and characterized by the presence of primitive or atypical myeloid or lymphoid cells in the bone marrow and the blood. "Positively correlated genes such as CDKN2B and ZIC2 were reported to have anti-leukemia effects." (PMID 32209730, 2020).
malignant ovarian tumors (2 papers, 2013 to 2015). "ZIC2 expression was revealed to correlate with a worse clinical course of ovarian cancer and oral cancer patients, while the molecular mechanism of ZIC2 expression in adult tumor cells and worse prognosis were not fully understood." (PMID 26318045, 2015). "For instance, ZIC2 was observed with a higher expression in malignant ovarian tumors and overexpression analysis showed oncogenic properties of ZIC2 to drive tumor growth in ovarian cancer." (PMID 24379827, 2013). "Overexpression analysis showed oncogenic properties of ZIC2 to drive tumor growth in ovarian cancer." (PMID 24379827, 2013). "ZIC2 was observed with higher expression in malignant ovarian tumors." (PMID 24379827, 2013).
medulloblastoma (2 papers, 2010 to 2021). A malignant, invasive embryonal neoplasm arising from the cerebellum. "ZIC1 is predominantly expressed in medulloblastoma, and ZIC2 expression is down-regulated in medulloblastoma compared to its mRNA level in normal cerebellum." (PMID 20199689, 2010). "However, the expression of the other ZIC genes (ZIC2, ZIC3, ZIC4, and ZIC5) has not been investigated in medulloblastoma or other brain tumors." (PMID 20199689, 2010).
melanoma (2 papers, 2019 to 2023). A malignant, usually aggressive tumor composed of atypical, neoplastic melanocytes. "Moreover, MYC (log FC = −3.32), PPARG (log FC = 2.17), ZIC2 (log FC = 3.62) were also dysregulated in melanoma." (PMID 31681565, 2019).
non-small cell lung carcinoma (2 papers, 2022 to 2023). A group of at least three distinct histological types of lung cancer, including non-small cell squamous cell carcinoma, adenocarcinoma, and large cell carcinoma. "ZIC2 promoted tumorigenesis and anoikis resistance of non-small-cell lung cancer (NSCLC) by FAK/Src signaling, verified in NSCLC patients." (PMID 36230714, 2022).
oral cancer (2 papers, 2015 to 2024). "The upregulation of ZIC2 was remarkably associated with the malignant clinical progression of oral cancer." (PMID 38304730, 2024). "The relatively higher expression level of ZIC2 presented by lymph node metastasis group, advanced clinical grade group, and positive HPV status group implicated that ZIC2 overexpression might promote the clinical progression of oral cancer." (PMID 38304730, 2024). "We also performed in vitro experiments and calculated drug sensitivity of oral cancer with different ZIC2 expression levels in response to hundreds of compounds." (PMID 38304730, 2024). "In the current study, the expression pattern and clinicopathological significance of ZIC2 in oral cancer were clearly characterized through integrated analysis of in-house tissue microarray, global RNA-seq, and microarrays containing large samples." (PMID 38304730, 2024). "The molecular basis of ZIC2 in oral cancer was further investigated in the aspects of transcription network and immune correlations." (PMID 38304730, 2024). "Relatively lower ZIC2 expression was observed in oral cancers of oral cavity, lip, hard palate, and normal base of the tongue and floor of mouth tissues." (PMID 38304730, 2024). "The integrated expression analysis results for all in-house and external datasets confirmed overexpression of ZIC2 in oral cancer as well as the good distinguishing performance (SMD = 1.31, 95% CI = 0.73 − 1.89; AUC = 0.89)." (PMID 38304730, 2024). "We demonstrated the upregulation of ZIC2 in oral cancer and its promoting effect on the clinical advancement of oral cancer." (PMID 38304730, 2024). "Oral cancer patients with higher ZIC2 expression showed higher drug sensitivity to two compounds including AZD8186 and ERK_2240." (PMID 38304730, 2024). "It was predicted that oral cancer patients with relatively higher ZIC2 expression were more sensitive to two compounds including AZD8186 and ERK_2240 than oral cancer patients with lower ZIC2 expression (P < 0.05)." (PMID 38304730, 2024). "We found high level of ZIC2 expression oral cancers on the base of the tongue, buccal mucosa, oropharynx, and normal oral cavity and oral tongue tissues." (PMID 38304730, 2024). "The aberrant expression of ZIC2 in oral cancer is capable of differentiating between oral cancer patients with or without lymph node metastasis." (PMID 38304730, 2024). "The upregulation of ZIC2 demonstrated preferable discriminating ability for oral cancer tissues (AUC = 0.980)." (PMID 38304730, 2024). "We explored the expression pattern and clinicopathological significance of ZIC2 in oral cancer through performing in-house tissue microarray and integrated analysis global RNA-seq and microarrays containing large samples." (PMID 38304730, 2024). "It would be interesting to investigate the impact of the two compounds on the expression level and oncogenic effect of ZIC2 in oral cancer in future studies." (PMID 38304730, 2024). "Association analysis of ZIC2 expression and clinicopathological parameters of oral cancer patients revealed remarkable correlation between ZIC2 expression and higher clinical grade and positive HPV status (P < 0.05)." (PMID 38304730, 2024). "However, the specific expression profile, clinicopathological significance, and mechanism of ZIC2 in oral cancer were unclear." (PMID 38304730, 2024). "The results from in vitro experiments in the present work verified the essential role of ZIC2 in the proliferation, migration, and invasion of oral cancer; nevertheless, more experiments were needed for exploring the function of ZIC2 in other biological processes and KEGG pathways of oral cancer." (PMID 38304730, 2024). "Hereby, we hypothesized that ZIC2 might also coact with these functional partners to affect the biological behaviors of oral cancer cells." (PMID 38304730, 2024). "All data unanimously proved the significant overexpression of ZIC2 in oral cancer." (PMID 38304730, 2024).
oral cancer (continued). "Therefore, we evaluated the relationships between ZIC2 expression or copy number and the infiltration of immune cells in oral cancer or head and neck cancer." (PMID 38304730, 2024). "We also identified miRNAs that might modulate the expression of ZIC2 and the theoretical transcriptional binding site of ZIC2, which implied potential regulation axis of transcription and expression centered around ZIC2 in oral cancer." (PMID 38304730, 2024). "Finally, we concentrated on genes differentially expressed between low and high ZIC2 expression groups of oral cancer and explored their functional enrichment in oral cancer." (PMID 38304730, 2024). "After obtaining the analysis results of the oncogenic potential of ZIC2 and its remarkable correlation with immune infiltration in oral cancer, we were curious about drugs which might show improved efficacy in oral cancer patients with high expression of ZIC2 and scored the drug sensitivity." (PMID 38304730, 2024). "Herein, the anticancer potential of ZIC2 in a wide type of human cancers inspired us that ZIC2 might also showed abnormal expression in oral cancer and played crucial roles in the occurrence and progression of oral cancer." (PMID 38304730, 2024). "To test the performance of overexpressed ZIC2 in risk stratification of the overall survival probability of oral cancer patients, we carried out survival analysis and the results revealed no significant prognostic value of ZIC2 expression for oral cancer patients." (PMID 38304730, 2024). "Thus, the association between ZIC2 expression and the prognosis of oral cancer patients could not be firmly established based on the analysis results in the present study." (PMID 38304730, 2024). "The expression pattern of ZIC2 in oral cancer and noncancer oral tissues of different parts from RNA-seq dataset was also analyzed." (PMID 38304730, 2024). "According to the statistical analysis for expression data of in-house tissue microarray, ZIC2 expression was significantly higher in 159 oral cancer tissues compared with that in 48 noncancer oral tissues (7.89 ± 1.994; 1.46 ± 1.868, P < 0.05)." (PMID 38304730, 2024). "With regard to immune infiltration in oral samples with different copy numbers of ZIC2, the infiltration level of CD8+ T cell, dendritic cells, and neutrophil was notably higher in oral cancer samples with high amplification than that in other types of oral cancer (P < 0.05)." (PMID 38304730, 2024).
pancreatic cancer (2 papers, 2015 to 2019). "It was recently confirmed that ANXA8 induced HIF-1α transcription via calcium signaling pathways in pancreatic cancer, and can be regulated by zinc-finger transcription factor ZIC2 to inhibit apoptosis." (PMID 31474227, 2019).
pancreatic ductal adenocarcinoma (2 papers, 2018 to 2020). An infiltrating adenocarcinoma that arises from the epithelial cells of the pancreas. "Earlier studies established the oncogenic role of ZIC2 in pancreatic ductal adenocarcinoma cells by activating the expressions of FGFR3 and ANXA836." (PMID 32066655, 2020). "In pancreatic ductal adenocarcinoma ZIC2 knockdown induced cell apoptosis and ZIC2 over-expression enhanced the cellular proliferation." (PMID 30197753, 2018).
renal carcinoma (2 papers, 2022 to 2023). A carcinoma arising from the epithelium of the renal parenchyma or the renal pelvis. "In vivo and in vitro experiments confirmed that ZIC2 regulated cell cycle and promoted cell proliferation, invasion, and metastasis of renal cancer cells." (PMID 37496990, 2023). "However, some of these genes, such as RNASET2, TF, and ZIC2, were already known to have an oncogenic role in the tumorigenesis, progression, and metastasis of renal cancer." (PMID 36463181, 2022).
schizophrenia (2 papers, 2012 to 2015). A major psychotic disorder characterized by abnormalities in the perception or expression of reality. "Some have been associated with neurodevelopmental disorders: schizophrenia (DIXDC1, ARVCF, MAGI2, ZIC2), ADHD (attention deficit/hyperactivity disorder) (TCERG1L), movement disorders (NOL3, TP53INP2), Huntington’s disease (H2AFY2, AGPAT1), Parkinson’s disease (LMX1B), and autism (PLXNA4, WNT2)." (PMID 25748564, 2015).
alcoholism (1 paper, 2023). "HPE has a heterogeneous etiology, potential causes include maternal diabetes, alcoholism, infections during pregnancy, drugs such as retinoic acid, chromosomal syndromes such as trisomy 13, and recessive autosomal mutations like SHH, SIX3, and ZIC2." (PMID 36845789, 2023).
arachnoid cyst (1 paper, 2019). Intracranial or spinal cavities containing a cerebrospinal-like fluid, the wall of which is composed of arachnoidal cells. "Arachnoid cyst, to best of our knowledge, has not been reported in patients with ZIC2 mutations." (PMID 30855487, 2019).
autism spectrum disorder (1 paper, 2017). A spectrum of developmental disorders that includes autism, and Asperger syndrome. "Our results suggest that EZH2 is involved in regulating ZIC2 and SHANK1 which have been linked to neurological diseases such as autism spectrum disorder." (PMID 28720872, 2017).
basal cell carcinoma (1 paper, 2021). A carcinoma involving the basal cells.
benign prostatic hyperplasia (1 paper, 2025). A non-cancerous nodular enlargement of the prostate gland. "Our previous report emphasized that chronic exposure to cadmium (10 μM) over one year led to the transformation of benign prostatic hyperplasia (BPH1) cells into malignancy through the ZIC2 signaling pathway (cerebellar zinc pathway)." (PMID 40520016, 2025).
coloboma (1 paper, 2020). An abnormality in which a part of a structure in one or both eyes is missing. "As discussed in this review, this common phenotype of microphthalmia and coloboma is exhibited when there is genetic disruption of neural plate border genes (Msx1/2, Zic2, and Tfap2) or neural crest specification genes." (PMID 33182738, 2020).